IL6R (interleukin 6 receptor)
Diseases named in the same sentence as IL6R in open-access papers (continued):
Sharing a sentence is not in itself a finding about the gene and the disease.
intrahepatic cholangiocarcinoma (2 papers, 2022 to 2024). A carcinoma that arises from the intrahepatic bile duct epithelium in any site of the intrahepatic biliary tree. "In human intrahepatic cholangiocarcinoma, vascular‐derived vCAFs have been found to be strongly associated with tumour cells through the IL‐6/IL‐6R axis, which not only promote the occurrence of tumours but also further mediate their progression and invasion." (PMID 38158643, 2024). "Moreover, vCAFs promoted the occurrence and development of intrahepatic cholangiocarcinoma through the IL‐6/IL‐6R signalling pathway and promoted the dry nature of tumour cells." (PMID 38158643, 2024).
leprosy (2 papers, 2013 to 2020). Leprosy is a chronic infectious disease affecting primarily the skin and peripheral nervous system. "To validate whether enhanced IL-6R expression on CD4+ T cells is causative of elevated IL-17A response in T1R leprosy patients, we studied the effect of blocking of IL-6R and IL-23R in MLSA induced IL-17A production by PBMCs cells in-vitro." (PMID 32934336, 2020). "Secondly, M. leprae (MLSA) antigen activates IL-6R to produce IL-17A by CD4+ T cells from T1R leprosy patients." (PMID 32934336, 2020). "In the present study, using IL-6 receptor (IL-6R)-blocking antibody, we examined the effects of IL-6 blockade on leprosy reactions, in light of Th17 cell differentiation." (PMID 32934336, 2020). "In summary, our present study for the first time reports that CD4+IL6R+ T cells are involved in IL-17A production in T1R leprosy patients." (PMID 32934336, 2020). "Subsequently, consistent with our previous findings in patients with T1R leprosy, we found IL-6R and IL-6 expression in stimulated PBMC cells, correlated with the Th17 response in T1R." (PMID 32934336, 2020). "Subsequently, IL-6R and IL-23R blocking experiments showed significantly (p < 0.002) down regulated IL-17A in T1R reaction as compared to NR leprosy patients." (PMID 32934336, 2020). "Taken together our data supports the greater role of IL-23 and its ligand IL-23R in leprosy as compared to IL-6/IL-6R for IL-17 production in both circulating cells and at the site of the dermal lesions." (PMID 23936569, 2013). "Because proliferation of M. leprae antigen-specific Th17 cells depend on TCR engagement with high IL-6R expression and is correlated with specific IL-17A response in our study, this mechanism explains the increased IL-6R expression in T1R as compared to NR leprosy individuals in this study." (PMID 32934336, 2020). "Surprisingly, the association of IL-23R and not IL-6R with IL-17+ cells in NR leprosy patients is not well studied." (PMID 32934336, 2020). "It appears that IL-23R was more relevant in leprosy than IL-6R reported to function in a similar manner indicating that the pathway of Th17 may show subtle differences not only in man as compared to the mouse but also in different diseases." (PMID 23936569, 2013). "After checking the status of IL-6R+ and IL-23R+ Th17 cells in reactional states, we were next interested in the secretion status of IL-17 via Th17 cells with or without MLSA, r-IL-6, r-TGF-β and r-IL-23 in both T1R and NR leprosy patients." (PMID 32934336, 2020). "Of interest, gene expression of IL-6R and IL-23R in T1R and NR patients in 48 h MLSA stimulated PBMC showed a significant increase (p < 0.01, p < 0.002) in T1R as compared with NR leprosy patients." (PMID 32934336, 2020).
lumbar spinal stenosis (2 papers, 2017 to 2021). A spinal stenosis that involves the lumbar region of vertebral column. "Patients with radicular pain caused by lumbar spinal stenosis, who received epidural injections of the anti-IL-6R monoclonal antibody tocilizumab, showed improvement in lower back and leg pain." (PMID 28819180, 2017). "In addition, clinical trials have also found that patients with lumbar spinal stenosis-induced sciatica injected with anti-IL-6R monoclonal antibody (tocilizumab) via epidural injection can effectively reduce radicular leg pain and numbness." (PMID 34769297, 2021).
malaria (2 papers, 2023 to 2025). Malaria is a serious and sometimes fatal disease caused by a parasite that commonly infects a certain type of mosquito which feeds on humans. "In this study, we investigated whether SNPs that were selected on the basis of interrupting IL6R and assumed to be a proxy for IL-6 signaling are associated with severe malaria case status." (PMID 36801374, 2023). "Previously, malaria-induced lethality in mice infected with P. chabaudi has been shown to be overcome by interrupting the alternative IL-6 trans-signaling pathway mediated by IL-6 bound to the soluble (s)IL-6Rα." (PMID 40243929, 2025).
medulloblastoma (2 papers, 2015 to 2020). A malignant, invasive embryonal neoplasm arising from the cerebellum. "When hAT-MSCs were co-cultured with medulloblastoma-BTICs, the expression levels of CCR4, CCR5, CCR7, XCR1, CXCR1, CXCR4, PDGFR-bb, KDR and TEK were increased, while the levels of CX3CR1, IL1R, IL6R, IL8R, IGF1R and CD44 were decreased (p<0.05)." (PMID 26076490, 2015).
migraine (2 papers, 2020 to 2021). "A recent biocomputational genetic association analysis of migraine and RA demonstrated that there is a phylogenetic relationship between the genes responsible for migraine and RA, such as SLC24A3 and HLA-B, MPPED2 and STAT4, and ATP1A2 and IL6R, respectively." (PMID 35281991, 2021).
mucoepidermoid carcinoma (2 papers, 2015 to 2023). A carcinoma morphologically characterized the presence of cuboidal mucous cells, goblet-like mucous cells, squamoid cells, cystic changes, and a fibrotic stromal formation. "Collectively, these results demonstrate that the effect of tocilizumab in the cancer stem cell fraction correlates with the increased expression of its target receptor (IL-6R) in mucoepidermoid carcinoma stem cells." (PMID 26287605, 2015). "Considering the prominent role of STAT3 signalling in the biology of cancer cells, these results provide further support to the therapeutic potential of IL-6R inhibition with tocilizumab in mucoepidermoid carcinoma." (PMID 26287605, 2015). "Here, we evaluated the anti-tumor effect of tocilizumab, a humanized anti-human IL-6R antibody, in combination with conventional chemotherapy (cisplatin or paclitaxel) in preclinical models of mucoepidermoid carcinoma." (PMID 26287605, 2015). "The results of this pilot experiment suggested that IL-6R inhibition with tocilizumab have a therapeutic effect in preclinical models of mucoepidermoid carcinoma, and informed our decision to decrease the dose of paclitaxel to 15 mg/kg for the remaining studies." (PMID 26287605, 2015). "Here, we investigated whether inhibition of IL-6 receptor (IL-6R) signaling with tocilizumab (humanized anti-human IL-6R antibody) sensitizes MEC to chemotherapy using human mucoepidermoid carcinoma cell lines (UM-HMC) and correspondent xenograft models." (PMID 26287605, 2015). "Here, we showed that therapeutic inhibition of IL-6R with tocilizumab has no measurable effect on mucoepidermoid carcinoma cell viability, cell cycle, or sphere formation in vitro." (PMID 26287605, 2015). "We observed that therapeutic inhibition of IL-6R with tocilizumab enhanced the in vivo anti-tumor effect of both conventional chemotherapeutic agents tested here, despite having no direct effect on the survival of unsorted mucoepidermoid carcinoma cells in vitro." (PMID 26287605, 2015).
Non-alcoholic fatty liver disease (2 papers, 2022 to 2024). "A target-based Mendelian randomization was used to investigate the efficacy of interleukin-6 receptor (IL-6R) blockage, which has been licensed for inflammation-associated disorders, in the treatment of non-alcoholic fatty liver disease." (PMID 38535313, 2024). "Overall, the results of this Mendelian randomization research indicated that IL-6R blockage may raise the risk of non-alcoholic fatty liver disease by blocking the IL-6 signaling pathway." (PMID 38535313, 2024). "For instance, in “Non-alcoholic fatty liver disease” pathway, IL6 activates its receptor IL6R and regulates the activity of lipogenic enzymes through SOCS3 and SREBP-1c to influence de novo fatty acid synthesis." (PMID 35237299, 2022).
parasitemia (2 papers, 2022 to 2023). "Different haplotypes of IL6 gene or IL6R genes have been related to IL-6 and other cytokine serum levels in humans, including IL-2, IL-8 and IL-18 cytokines, and with the severity or protective effect of the infectious disease, including parasitic diseases." (PMID 36759910, 2023). "We found that a combination of an early recombinant IFN‐α/β injection at 18 h p.i. with an administration of anti‐IL‐6R antibodies at day three p.i. could reduce parasitemia and prolong mouse survival." (PMID 35635376, 2022). "In contrast, WT mice treated with a recombinant IFN‐α/β at 18 h or anti‐IL6R antibodies at day three p.i. failed to generate strong immunity, leading to high parasitemia levels and mortalities within 10 days p.i.." (PMID 35635376, 2022).
Parkinson disease (2 papers, 2023 to 2024). A progressive degenerative disorder of the central nervous system characterized by loss of dopamine producing neurons in the substantia nigra and the presence of Lewy bodies in the substantia nigra and locus coeruleus. "Our research underscores the potential value of targeting the IL6R pathway in the prevention and treatment of Parkinson’s disease." (PMID 39229261, 2024).
peripheral nerve injury (2 papers, 2020 to 2022). Injury to a peripheral nerve. "Moreover, in peripheral nerve injury, IL-6, IL-6R, and gp130 (a signal transducer of IL6R) are overexpressed, making it possible to cause significant pain hypersensitivity." (PMID 32867013, 2020).
Peritoneal Fibrosis (2 papers, 2014). Disorder characterized by a wide range of structural changes in PERITONEUM, resulting from fibrogenic or inflammatory processes. "In this context, SES activates Th1 cell expansion in a IL-6Rα-dependent manner, which promotes enhanced stromal STAT1 signaling as an early prerequisite to the onset of peritoneal fibrosis." (PMID 24412616, 2014).
preeclampsia (2 papers, 2021 to 2022). Preeclampsia is a hypertensive disorder of pregnancy that is characterized by new-onset hypertension with proteinuria presenting after 20 weeks of gestation, and depending on mild or severe forms may initially present with severe headache, visual disturbances, and hyperreflexia. "The current study aims to evaluate the association of SNP rs2229238 in the interleukin 6 receptor alpha (IL6RA) gene with the risk of preeclampsia." (PMID 35673309, 2022). "The main intention of this study is to assess the interleukin 6 receptor alpha (IL6RA) SNPs and their association with the risk of preeclampsia." (PMID 35673309, 2022).
primary Sjögren’s Syndrome (2 papers, 2022). "IL6R was also the target of a drug that we identified and has been evaluated in a clinical trial for its efficacy in primary Sjögren’s Syndrome (pSS) patients (NCT01782235)." (PMID 35268532, 2022).
prostate adenocarcinoma (2 papers, 2020 to 2021).
relapsing-remitting multiple sclerosis (2 papers, 2013 to 2019). The most common clinical variant of multiple sclerosis, characterized by recurrent acute exacerbations of neurologic dysfunction followed by partial or complete recovery. "This is consistent with recent data from patients with active relapsing-remitting multiple sclerosis where Teff hyperactivity mediated by increased IL-6R signaling renders them resistant to Treg suppression." (PMID 31781109, 2019).
renal carcinoma (2 papers, 2016 to 2021). A carcinoma arising from the epithelium of the renal parenchyma or the renal pelvis. "A monoclonal antibody, CNTO 328 (siltuximab) inhibits JAK/STAT3 signaling and IL-6/IL-6R/gp130 trans-signaling by interfering with the binding of IL-6 and IL-6R and has shown encouraging results in early trials in ovarian and renal cancers." (PMID 33671547, 2021).
Salmonella Infections (2 papers, 2011 to 2022). Infections with bacteria of the genus SALMONELLA. "Combined with the cytokine receptor phosphorylation data discusses previously (IL2R and IL6R), it is reasonable to assume that STAT5B phosphorylation found here is involved in maintaining the cecal function during the initial Salmonella infection stage." (PMID 35846741, 2022).
soft tissue sarcoma (2 papers, 2020 to 2022). A malignant neoplasm arising from muscle tissue, adipose tissue, blood vessels, fibrous tissue, or other supportive tissues excluding the bones. "High expression of IL-6R was also observed and indicated a poor prognosis for overall survival and metastasis-free survival in patients with soft tissue sarcomas." (PMID 36091805, 2022). "This study aimed to elucidate the association between IL-6 and IL-6 receptor (IL-6R) expression in tissues and clinical outcomes in patients with soft tissue sarcomas (STSs) because, to our knowledge, this has not been done before." (PMID 32138303, 2020).
synovitis (2 papers, 2022). Inflammation of a synovial membrane. "We confirmed that CRP serum levels are not a biomarker of active synovitis in patients under anti-IL-6R therapy, as shown by previous reports." (PMID 35054349, 2022). "In the anti-IL-6R group, hsCRP did not correlate with the composite activity index or US synovitis." (PMID 35054349, 2022). "Therefore, it has been suggested that CRP serum levels and, by extension, disease activity scores containing this APR are not sensitive markers of inflammation (synovitis) in patients treated with anti-IL-6R or JAKi, in contrast to other biological therapies, such as TNF inhibitors." (PMID 35054349, 2022).
thyroid (2 papers, 2021 to 2022). "Previous results from our group demonstrated that ouabain (10−7 M) increased IL-6 and IL-6R mRNA levels in TPC-1, BCPAP (papillary carcinoma human thyroid cell lines) and NTHY-ori (non-tumoral human thyroid cell line) after 24 h of culture." (PMID 36551653, 2022).
thyroid nodule (2 papers, 2020). A small circumscribed mass in the THYROID GLAND that can be of neoplastic growth or non-neoplastic abnormality. "Also, IL-6R was found associated with the characterization of thyroid nodules’ malignancy and tumor aggressiveness." (PMID 32819324, 2020).
Ventricular arrhythmia (2 papers, 2021 to 2024). "QT interval is increased by +36% and +53%, for IL-6 and IL-6 + IL-6R, respectively, consistent with the signature high risk proarrhythmic effect that underlie fatal ventricular arrhythmias in patients." (PMID 34681909, 2021). "Therefore, it would also be valuable to explore the link between IL-6 + IL-6R, IKs and ventricular arrhythmias." (PMID 34681909, 2021).
Acute GVHD (1 paper, 2022). "Finally, we did not detect any difference in IL-6R expression when comparing circulating T cells and non-T cells derived from patients with and without previous acute GVHD." (PMID 35566660, 2022).
alcohol addiction (1 paper, 2023). "However, to our knowledge, there are no studies that focus on the genetic variability of PON1, SOD2, GPX1, IL1B, IL6, interleukin 6 receptor (IL6R), and miR146a related to the risk of alcohol addiction, and patients’ comorbid psychosymptomatology." (PMID 38275640, 2023). "Thus, we focused on the role of PON1 rs705379, rs705381, rs854560, and rs662, SOD2 rs4880, GPX1 rs1050450, IL1B rs1143623, rs16944, and rs1071676, IL6 rs1800795, IL6R rs2228145, and miR146a rs2910164 in alcohol addiction, and patients’ comorbid psychosymptomatology." (PMID 38275640, 2023).
appendicitis (1 paper, 2015). Acute inflammation of the vermiform appendix. "IL-6 (-572G/C rs1800796) and IL-6R (1:G.154448302 T > C rs7529229) gene polymorphisms may have an impact on cytokine production, immune response and these gene polymorphisms may be used as inflammatory markers in the diagnosis of appendicitis." (PMID 26714766, 2015).
asthenia (1 paper, 2024). Clinical sign or symptom manifested as debility, or lack or loss of strength and energy. "Concerning the comparison between Ctrl and Anti-IL-6-R, respiratory comorbidities, headache, asthenia, arthralgia, syncope, Raynaud’s phenomenon, oxygen therapy, post-COVID diarrhea, post-COVID headache, post-COVID cough and post-COVID dyspnea on exertion entered the ranked ANCOVA." (PMID 38248262, 2024).
B cell deficiency (1 paper, 2020). A broad classification of disorders where circulating numbers of B lymphocytes are decreased or ineffective. "Contrary to IL-6R inhibition of TH17-EAE, we found that B cell-deficiency attenuates disease in TH17-EAE regardless of IFN-β treatment." (PMID 32503977, 2020).
B cell lymphoma (1 paper, 2006). "This kind of therapy is not recommended for B cell lymphoma, as these cells have no IL-6R." (PMID 16892169, 2006).
cardioembolic stroke (1 paper, 2021). "A more recent Mendelian randomization study on the other hand found an association between IL6R and the risk of large vessel stroke but not cardioembolic stroke." (PMID 34372806, 2021).
cataract (1 paper, 2020). Partial or complete opacity of the crystalline lens of one or both eyes that decreases visual acuity and eventually results in blindness. "The level of IL-12p40, MIP-1d, IL-7, IL-6R, BLC, TNF-a, IL-5 were elevated in the SG samples compared to the samples of the cataract patients." (PMID 32117217, 2020).
cerebral aneurysms (1 paper, 2024). "Secondly, elevation in progranulin (OR: 1.7069, 95% CI: 1.0654-2.7345, PIVW: 0.0262), TRAIL-R3 (OR: 2.1605, 95% CI: 1.2297-3.7959, PIVW: 0.0074), and IL-6R (OR: 2.4218, 95% CI: 1.0512-5.5795, PIVW: 0.0378) was associated with an increased risk of cerebral aneurysm." (PMID 39253091, 2024). "Our study identified a positive correlation between IL-6R and cerebral aneurysms." (PMID 39253091, 2024).
cerebral infarction (1 paper, 2020). An ischemic condition of the brain, producing a persistent focal neurological deficit in the area of distribution of the cerebral arteries. "In vivo administration of 50 ng IL-6 reduced cerebral infarction, restored SOD-2 expression via IL-6R-STAT3 pathway, and blocked the oxidation and dissociation of IL-6R and gp130." (PMID 33317180, 2020).
cervical (1 paper, 2019). "Although many studies have focused on IL-6 and its involvement in cervical carcinogenesis, there are few reports on IL-6R and its implication in CC." (PMID 31396215, 2019).
cherubism (1 paper, 2018). Cherubism is a rare, self-limiting, fibro-osseous, genetic disease of childhood and adolescence characterized by varying degrees of progressive bilateral enlargement of the mandible and/or maxilla, with clinical repercussions in severe cases. "As cherubism was recently described as being an auto-inflammatory bone disease, we focused on the expression of genes involved in osteoclastogenesis (RANK, RANKL, M-CSF, OPG, NFATc1), bone formation (ALP, Osteocalcin), and inflammation (IL6, IL6R, TNFα, TNFR1, TNFR2, IL17)." (PMID 30236129, 2018).
CNS lymphoma (1 paper, 2023). "In addition, EVs bearing these molecules were significantly and positively associated with non-CNS lymphoma: PD-L1 (OR = 1.94; 95% CI: 1.01 – 3.72); CD40 (OR = 2.66; 95% CI: 1.12 – 6.35); TNF-RII (OR = 9.64; 95% CI: 2.52 – 36.86); IL-6Rα (OR = 8.34; 95% CI: 1.73 – 40.15)." (PMID 37809067, 2023).
craniopharyngioma (1 paper, 2019). A benign, partly cystic, epithelial tumor of the sellar region, presumably derived from Rathke pouch epithelium. "Evidence from our group and others has shown that the cystic and solid tumor components of craniopharyngioma have high levels of IL-6R and IL-6, providing a potential target for therapy." (PMID 31497533, 2019).